CTSD (cathepsin D)
Diseases named in the same sentence as CTSD in open-access papers (continued):
Sharing a sentence is not in itself a finding about the gene and the disease.
breast carcinoma (continued). "The proteomic comparisons notably led to the identification of five proteins that are used as breast cancer diagnostic and prognostic biomarkers: proliferating cell nuclear antigen (PCNA), cathepsin D, cathepsin B, protein S100-A14, and heat shock protein beta-1 (HSP27)." (PMID 22384035, 2012). "Cathepsin D was suggested as one of the c-Myb-target genes in MCF7 breast cancer cells previously." (PMID 22439866, 2012). "In this regard, it was shown that cathepsin D activity in corpora lutea varies along the estrous cycle and that estradiol increases the activity and synthesis of cathepsin D in uterus and in ovarian and breast cancer cells." (PMID 21760910, 2011). "There is controversy regarding the prognostic value of cathepsin-D in primary breast cancer." (PMID 9888472, 1999). "The expression of the protease cathepsin-D has been evaluated using an immunohistochemical technique with a polyclonal antibody in paraffin-embedded tissue from 359 patients treated between the years 1975-1981 for Stage I and II breast cancer." (PMID 8471433, 1993). "The effects of tamoxifen, three of its in vivo metabolites and 3-hydroxytamoxifen on cellular proliferation and the induction of four oestrogen-regulated RNAs (pNR-1, pNR-2, pNR-25 and cathepsin D) have been measured in MCF-7 breast cancer cells in phenol red-free culture medium." (PMID 2736207, 1989). "Consequently, evaluating Cathepsin D expression in breast cancer prior to initiation of hormonal therapy may predict anti-oestrogen responsiveness." (PMID 38578521, 2024). "Therefore, we can hypothesize that cathepsin D enhances migration/invasion of breast cancer cells via LRP1 signaling." (PMID 22439866, 2012). "Therefore, we analyzed the expression of candidate proteases in c-myb-overexpressing and control MDA-MB-231 cells and confirmed the differential expression of MMP1, MMP9, and cathepsin D. We confirmed the recent observation by Bhattarai that the c-Myb upregulates MMP9 in breast cancer cells." (PMID 22439866, 2012). "CTSL, CTSD, and HSPA8 were down-regulated in breast cancer cells, and their overexpression attenuated malignant behaviors of TNBC cells." (PMID 41399382, 2026). "The transcript expressions of CTSD, EGFR, CNND1, and BCL2 in breast cancer patients can be observed in the box plots." (PMID 39202273, 2024). "TIMER2.0 was used to estimate the correlations between ESR1, with a purity adjustment, and the expression of CTSD, EGFR, CCND1, and BCL2 in breast cancer subtypes." (PMID 39202273, 2024). "This study found that estradiol can increase the expression of cation-dependent mannose-6-phosphate receptor (CD-MPR) and cathepsin D (CatD) and alter their distribution in MCF-7 breast cancer cells." (PMID 38203393, 2023). "Previous studies also support our findings with research implicating that nuclear CTSD and CTSL can also impact on cell cycle progression in breast cancer and colorectal cancer cell lines respectively." (PMID 38026973, 2023). "By using siRNAs targeting all three TETs, expression of CTSD and CLN3 was shown to be specifically repressed by TET2 in MCF-7 and T47D breast cancer cells and, to a lower extent, in HEK293T kidney cancer cells." (PMID 35351824, 2022). "The heatmap showed that the HMGA1-high cluster expressed TMSB10, CTSD and LGALS1, which are correlated with poor prognosis in breast cancer." (PMID 35611554, 2022). "Lucanthone, a novel autophagic inhibitor, induces apoptosis via cathepsin D accumulation and enhances histone deacetylase inhibitor (vorinostat)-induced cell death in MDA-MB-231 breast cancer cells." (PMID 35008442, 2021). "Both CTSD and CA9 are the important targets that have reported the therapeutic effects on breast cancer." (PMID 32420359, 2020).
breast carcinoma (continued). "Taken together, cathepsin D can modulate the expression of HER2, as well as ER, and influence the ability of proliferation, survival, invasion, and metastasis in the luminal breast cancer cells." (PMID 32846884, 2020). "In a biochemical assay that checks the leakage of lysosomal enzymes into the cytosol, we observed a pronounced leakage of both cathepsin D and cathepsin B to the cytosol in PC3 prostate and MDA-MB-231 breast cancer cells." (PMID 31412041, 2019). "In the case of cathepsins, CTSB, CTSD, CTSK, CTSL, and CTSS were expressed in all breast cancer cells; however, the mRNA and protein expression of CTSS was much higher in the TNBC cell lines compared to the hormone-responsive cell lines." (PMID 30185799, 2018). "These chromosomes contain genes that are commonly involved in the invasion, metastasis and pathogenesis of breast cancer, including c-MYC on 8q24; HRAS, CD151, CTSD on 11p15; CCND1 on 11q13; and TOP2A on 17q21." (PMID 24456987, 2014). "An additional protein family of interest is the CTS proteins; in the present study, five CTS proteins (CTSB, CTSC, CTSD, CTSH and CTSZ) were identified to be upregulated in breast cancer." (PMID 24932247, 2014). "A constitutively active mutant of AhR that was designed to mimic continuous TCDD activation also inhibited expression of estrogen-dependent cathepsin D and attenuated the estrogen-induced growth of MCF-7 human breast cancer cells." (PMID 25068070, 2013). "Rab27A has effects on the invasive and metastatic potentials of breast cancer cells by modulating the secretion of IGF-II, which regulates the expression of p16, VEGF, uPA, cathepsin D, cyclin D1, and MMP-9." (PMID 23977139, 2013). "Down-regulation of cathepsin D and TFF1/PS2 has also been reported in antihormone treated breast cancer cells." (PMID 22417809, 2012). "For instance, cathepsin D (CTSD), which is an estrogen-inducible lysosomal protease identified in breast cancer, is considered to be a critical factor in mediating apoptosis of cancer cells, neurodegeneration, and development regression." (PMID 22291950, 2012). "Recently, one report showed that Rab27a affects the invasive and metastatic potential of breast cancer cells by modulating the secretion of IGF-II, which regulates the expression of p16, VEGF, uPA, cathepsin D, cyclin D1, and MMP-9." (PMID 23029308, 2012). "The concentrations of cathepsin D (Cath D), urokinase (uPA) and two plasminogen activator inhibitors (PAI-1 and PAI-2) were analysed in the cytosols of 130 human mammary tumours (43 benign tumours and 87 primary and unilateral breast carcinomas)." (PMID 1931618, 1991). "Though OC-specific data are lacking, breast cancer studies show CTSD promotes mTOR-driven proliferation and M2 macrophage polarization, mechanisms compatible with the pro-metastatic TME features of our high-risk cohort." (PMID 40299498, 2025). "Patients in stages 3 and 4 of breast cancer subtypes such as Her2, Luminal A, and Luminal B who test positive for CCND1, CTSD, EGFR, BCL2, and ESR1 gene expression might benefit in this regard." (PMID 39202273, 2024). "Kaplan–Meier survival analysis of breast cancer-specific survival (BCSS) showed significantly poor prognosis for Cathepsin D-expressing tumours compared with those negative for the biomarker (p = 0.001)." (PMID 38578521, 2024). "In addition, recent studies have shown that cathepsin D can cleave CST3 under an acidic pH, leading to decreased CST3 expression in the breast cancer microenvironment." (PMID 37445705, 2023). "Along this line, RelB (non-canonical NF-κB activation) overexpression in breast cancer cells induced cathepsin D downregulation." (PMID 36612268, 2022). "Other studies demonstrated that mice with breast cancer that had a CTSD knockout (MMTV-PyMT-cre; CTSD−/−) elicited impaired mTOR signaling, which is an important downstream target of pAkt, suggesting that cathepsins are involved in this crucial cell survival and growth pathway." (PMID 36289617, 2022).
breast carcinoma (continued). "While the role of CTSD and CTSL has not been specifically demonstrated in HCC, CTSD has been shown to be directly involved in invasion and metastasis in various other cancer types, including breast cancer." (PMID 36289617, 2022). "To further understand the mechanism of these progestogens in breast cancer, we investigated whether P4, MPA, NET and DRSP could regulate the expression of the ER-regulated CTSD gene." (PMID 36187129, 2022). "It has also been documented that CTSD and GREB1 were increased in breast cancer patients." (PMID 33861751, 2021). "Cathepsin D (CTSD) is a lysosomal protease and a marker of poor prognosis in breast cancer." (PMID 33046706, 2020). "As mentioned in the previous section, it has been substantiated that the proliferation of breast cancer cells harboring the two conjoined genes, SCNN1A-TNFRSF1A and CTSD-IFITM10, could be decreased by targeting them with the corresponding siRNAs." (PMID 29414922, 2018). "We analysed a large and well-characterized cohort of breast cancer cases with complete data on classical prognostic factors and relevant molecular markers, such as oestrogen receptor (ER), progesterone receptor (PgR) and HER2 as well as Cathepsin D’s role in response to tamoxifen therapy." (PMID 38578521, 2024). "Unlike macrophages, which we have previously demonstrated not to undergo apoptosis after IR exposure, breast cancer cells exhibit increased cathepsin D expression and significant reduction of viability, upon exposure to single (10 Gy) or fractionated (5 × 2 Gy) radiotherapy doses." (PMID 36612268, 2022). "Down-regulation of CLN3, CTSD, and NAGLU in TET2 CD cells was further confirmed by RT-qPCR analysis, and expression of these three genes was shown to be anticorrelated with TET2 expression levels in the breast cancer TCGA cohort of patients (n = 1,218), validating our in vitro observations." (PMID 35351824, 2022). "Our studies demonstrated that a panel of biomarkers including cathepsin D, CK19, nucleophosmin and peroxiredoxin 2 would be applied as a set of indicators for breast cancer relapse, and they could also represent potential therapeutic targets under sufficient validation." (PMID 32846884, 2020). "We further detected significant increases in the levels of ZO-1, but N-cadherin showed remarkable downregulation after the diminishment of cathepsin D, as compared to the mock, suggesting that cathepsin D may promote EMT initiation and induce the relapse of breast cancer cells." (PMID 32846884, 2020). "However, the role of sortilin in cathepsin D transport in breast cancer cells should not be ruled out, since this receptor in known to participate in the sorting of lysosomal proteins including cathepsin D in other cell types." (PMID 30086159, 2018). "In MDA-MB-231 breast cancer cells this is probably due to the lack of mitogenic pro-CTSD secretion, although those knock-down studies could not discriminate between intra- and extracellular CTSD functions." (PMID 33046706, 2020). "Cathepsin D, CATD (CTSD) is an acid protease that is active in the breakdown of intracellular proteins, which has been reported to be involved in the pathogenesis of several diseases, such as breast cancer and possibly Alzheimer’s disease via non-proteolytic pathways." (PMID 30060564, 2018). "Immunofluorescence assays revealed abnormal expression of CTSL, CTSD, HSPA8, and XRCC4 in CD11b+ cells in tumor tissues than those in paracancerous normal tissues, regardless of breast cancer subtypes." (PMID 41399382, 2026). "Our study revealed a highly significant difference in breast cancer-specific survival (BCSS) between patients who received tamoxifen and those who did not, but only in patients with Cathepsin D-positive tumours (p = 0.025)." (PMID 38578521, 2024). "In patients with Basal or Her2 breast cancer, no substantial connection was identified between the ESR1 and CTSD gene expression." (PMID 39202273, 2024).
breast carcinoma (continued). "We found BPAF stimulated the endogenous transcription of TFF1, GREB1 and CTSD genes through both dose and time-dependent manners in ERα-positive T47D and MCF7 human breast cancer cells, but not in ERα-negative MDA-MB-231 cells." (PMID 24727858, 2014). "The expression of cathepsin D in the melanoma cell line (B16F10) was only slightly lower than that in the PyMT or RAW 264.7 cells, and we detected almost no expression of cathepsin D in the mammary carcinoma cell line (4T1)." (PMID 37896224, 2023). "To evaluate the effect of BPAF on endogenous transcription, we conducted the real-time PCR to detect mRNA levels of estrogen responsive genes, such as TFF1, GREB1 and CTSD in ERα-positive T47D and MCF7 breast cancer cell lines and ERα-negative MDA-MB-231 breast cancer cell line." (PMID 24727858, 2014). "Additionally, neither the active forms of lysosomal proteases cathepsin D nor the MTOR pathway were significantly altered in this process, indicating that autolysosomal degradation upon NUPR1 depletion is independent of the MTOR pathway in TamR breast cancer cells." (PMID 33542201, 2021).
Alzheimer disease (37 papers, 2007 to 2025). A progressive, neurodegenerative disease characterized by loss of function and death of nerve cells in several areas of the brain leading to loss of cognitive function such as memory and language. "Similar increases in neuronal cathepsin D and lysosomal storage material have been observed in degenerated regions of brains from patients with Alzheimer’s disease (AD), though these changes are closely associated with AD pathology." (PMID 37118844, 2023). "The polymorphism c.C224T (p.Ala58Val) located in exon 2 of the CTSD gene was associated with sporadic late-onset Alzheimer’s disease in the adult German, Iranian, and Ecuadorian populations." (PMID 34198733, 2021). "A molecular imaging probe to fluorescently image the β-site of the amyloid precursor protein (APP) cleaving enzyme 1 (BACE1) and cathepsin D (CatD) enzymes associated with Alzheimer’s disease (AD) was designed and synthesized." (PMID 31936569, 2020). "It has also been reported that altered expression of cathepsin D levels has been linked to Alzheimer's disease, indicating the possible role of cathepsin D in regulating tau degradation." (PMID 29375176, 2017). "Genetic variants in CtsD have been identified as a risk factor for Alzheimer's disease and increased immunostaining of CtsD has been reported in AD brains." (PMID 27902765, 2016). "Cathepsins B (CtsB) and D (CtsD) have been found at extracellular sites closely associated to senile plaques in patients suffering from Alzheimer's disease (AD)." (PMID 27902765, 2016). "Cathepsin D, a lysosomal aspartyl protease, has been implicated in the pathology of Alzheimer’s disease as well as breast and ovarian cancer." (PMID 23264933, 2012). "Nonetheless, a recent candidate gene analysis in a large population-based cohort study as well as a meta-analysis of previous studies supports the association of a CTSD variant and Alzheimer's disease risk." (PMID 20664788, 2010). "Polymorphisms in the cathepsin D-encoding gene CTSD have also been associated with Alzheimer's disease." (PMID 20664788, 2010). "This study looked at a polymorphism in the cathepsin D gene (refSNP ID: rs17571) previously examined in Alzheimer's disease (AD)." (PMID 18426579, 2008). "In addition to these pathogenic mutations that cause NCL disease, there are several other variants of the CTSD gene thought to be associated with other diseases, such as Parkinson's disease and Alzheimer's disease." (PMID 34331747, 2021). "Some forms of cathepsin D deficiency could also predispose to late-onset Alzheimer’s disease and Parkinson’s disease." (PMID 34198733, 2021). "Cathepsin D (CatD) is a lysosomal protease that degrades both the amyloid β-protein (Aβ) and the microtubule-associated protein, tau, and has been genetically linked to late-onset Alzheimer disease (AD)." (PMID 32631408, 2020). "Additionally, cathepsin D has also been linked to neurodegenerative disorders and in particular to Alzheimer's disease." (PMID 29375176, 2017). "Cathepsin D (CatD) is a lysosomal protease that degrades both the amyloid-β protein (Aβ) and the microtubule-associated protein, tau, which accumulate pathognomonically in Alzheimer disease (AD), but few studies have examined the role of CatD in the development of Aβ pathology and tauopathy in vivo." (PMID 38575959, 2024). "Therefore, cathepsin D can be used as a diagnostic biomarker for Alzheimer’s disease." (PMID 34198733, 2021). "Among these DEGs, certain genes associated with Alzheimer’s disease were identified, including Amyloid Beta Precursor Protein (APP), Presenilin 1 (PSEN1), and Cathepsin D (CTSD)." (PMID 40243634, 2025). "Recent studies have reported that endogenous proteases, including CD10, MMP9, cathepsin D, and cathepsin B, showed fibrinolytic capacity to amyloid-beta fibrils of Alzheimer's disease." (PMID 40302732, 2025).